TLR2 (toll like receptor 2)
Diseases named in the same sentence as TLR2 in open-access papers (continued):
Sharing a sentence is not in itself a finding about the gene and the disease.
metabolic syndrome (28 papers, 2012 to 2025). A cluster of metabolic risk factors for CARDIOVASCULAR DISEASES and TYPE 2 DIABETES MELLITUS. "TLR2-deficient mice were shown to have improved insulin sensitivity and reduced diet-induced metabolic syndrome." (PMID 31507457, 2019). "Further research could explore the mechanistic pathways underlying this association, such as the impact of TLR2 activation on triglyceride levels and whether interventions targeting TLR2 signaling could have therapeutic implications for managing dyslipidemia." (PMID 37400578, 2023). "As TLR4 is known to contributed to hyperlipidemia, we wondered whether the more severe dyslipidemia phenotype in TLR2-deficient offspring-pLPS was due to TLR4 activity." (PMID 31507457, 2019). "For instance, the Gram-positive bacteria binding receptor TLR2, which can also bind dietary fatty acids and plays a role in the progression of the metabolic syndrome, was upregulated in Acat2-overexpressing liver." (PMID 36378328, 2023). "Studies on persons with diabetes and metabolic syndrome (MetS) have reported upregulated levels of TLR2 and MyD88 genes." (PMID 31272370, 2019). "Research suggests that immune modulation of the gut microbiota induces symptoms of metabolic syndrome in Tlr2 knockout mice." (PMID 29113135, 2017). "The purpose of this study was to investigate the effects of dyslipidemia on osteoclast differentiation associated with TLR2 and TLR4 in periodontal tissues using a rat dyslipidemia (apolipoprotein E deficient) model." (PMID 23295061, 2013). "In conclusion, dyslipidemia induces osteoclast differentiation on the alveolar bone surface by activation of TLR2 and TLR4 in the rat apolipoprotein E knockout model." (PMID 23295061, 2013). "Another mechanism by which dyslipidemia may affect platelets is the Toll-like receptor 2 (TLR2) stimulation mechanism, which activates the aggregation process through lipid-peroxide-modified phospholipids in the transport of Lp(a), which plays an important role." (PMID 33808697, 2021). "Contradictory to our original hypothesis, we found that TLR2-deficiency promotes, rather than prevents, dyslipidemia in prenatal LPS-induced obese offspring." (PMID 31507457, 2019). "Enhanced TLR2 expression had previously been reported on monocytes from DM2 and metabolic syndrome patients." (PMID 33172487, 2020). "The plasma markers of this phenotype included: hyperglycemia, dyslipidemia and elevated plasma levels of ALT, leptin, TNFα and TLR2 and TLR4 activators." (PMID 26761430, 2016). "Gene expression of TLR2, TLR4 and RANKL was 1.90, 1.37, and 1.52 times higher in periodontal tissues obtained from the dyslipidemia group than in those obtained from the control group, respectively (p < 0.05)." (PMID 23295061, 2013). "The results demonstrated that age, dyslipidemia, atrial fibrillation, triglyceride, MR (grades 2 to 4), mean TLR2+/CD14+ cells, TLR2+/CD14+ cells <25%, TLR4+/CD14+ cells <0.25%, mean MPO+/CD14+cells, MPO+CD14+ cells <20%, sST2 <14,000 (pg/mL), and mean sST2 were significantly predictive of mild CCS." (PMID 32054047, 2020). "We found significantly downregulated CETP expression in offspring-pLPS independent of the TLR2 genotype, which might partly contribute to the dyslipidemia phenotype." (PMID 31507457, 2019).
Autoimmunity (27 papers, 2009 to 2025). The occurrence of an immune reaction against the organism's own cells or tissues. "Regarding autoimmunity, TLR2-deficient B6lpr/lpr mice develop a significantly less severe lupus-like disease than B6lpr/lpr, as demonstrated by the reduced intensity of glomerulonephritis and the decrease of autoantibody rates." (PMID 36353645, 2022). "Another TLR that has been implicated in inducing autoimmunity against nucleosomes is TLR2 which binds nuleosome-HMGB1 complexes." (PMID 24151519, 2013). "A total five genes (Fes, Aif1, Gata3, Tlr6, Tlr2) were identified as hub genes that are most likely related to the silicone-induced immune response, four of which (Aif1, Gata3, Tlr6, Tlr2) have been associated with autoimmunity as target genes or disease markers." (PMID 29245939, 2017). "In ANCA-associated vasculitis, TLRs play crucial roles in initiating autoimmunity and inflammation, which are primarily attributed to TLR-2-induced Th17 autoimmunity, while TLR-9 promotes Th1 autoimmunity." (PMID 36366292, 2022). "TLR2 is also found on the cell surface of microglia and astrocytes in the CNS, indicating that TLR2 plays a role in CNS autoimmunity, neurodegeneration, and tissue injury." (PMID 34135889, 2021). "A total five genes (Fes, Aif1, Gata3, Tlr6, Tlr2) and nine pathways were identified as central participants in the silicone-induced immune response, most of which are also related to autoimmunity." (PMID 29245939, 2017). "Strikingly, most of these hub genes (Tlr2, Tlr6, Aif1, Gata3) have also been reported to be crucial in autoimmunity development." (PMID 29245939, 2017). "Thus, our observations define Tlr2 as a molecular link between infectious history and modulation of the course of autoimmunity, in which, however, it plays a janus role." (PMID 27252700, 2016). "The present finding of intact sBGN in SF, together with the recognition of sBGN as an endogenous damage-associated molecular pattern-type ligand for TLR2/TLR4 and for P2X7/4, provides a third mechanism of relevance for autoinflammation, co-stimulation and autoimmunity." (PMID 26703441, 2015). "Based on these observation it is tempting to speculate that the anti-PsA peptide antibodies we describe here, may contribute to autoimmunity upon interaction with TLR2." (PMID 25514237, 2014). "In AAV, major toll-like receptor 2 (TLR2) and toll-like receptor 9 (TLR9) activation can provoke autoimmunity." (PMID 35632497, 2022). "Animal experiments have shown that pattern recognition receptors (PRRs) such as Toll-like receptor 2 (TLR2) can activate APCs such as DCs and macrophages to activate autoreactive T cells inducing β cell autoimmunity." (PMID 35937817, 2022). "Future studies should explore HMGB1’s interactions with TLR2/CD36 in B cells, its role in human autoimmune disorders, and whether its cytoskeletal functions intersect with metabolic pathways like oxidative phosphorylation, which was impaired in cKO B cells." (PMID 40985892, 2025). "Therefore, because TLR2 cannot recognize bacterial HSP60, perhaps the abnormal recognition of HSP60 by TLR4 is the beginning of normal autoimmunity in NTG." (PMID 20057905, 2009). "TLR2 and TLR4 silencing in CD14++ monocytes of these patients prevents Treg differentiation to Th1-like Tregs and thus IFN-γ secretion by Tregs of these patients, suggesting that autoimmunity is promoted by CD14++ monocytes predominantly through activation of inflammatory signaling pathways." (PMID 30072988, 2018). "Cleavage and release of the soluble TLR2 ectodomain suppresses TLR2 activity by binding and quenching DAMP ligands, an activity thought to reduce the development of autoimmunity through a negative feedback loop." (PMID 28437250, 2017). "TLR2 and TLR4 bind to components of gram positive and gram negative bacteria which could be a pathognomonic factor in autoimmunity." (PMID 26339139, 2015).
bacteremia (27 papers, 2009 to 2026). "Both aging and TLR2 deficiency impair the immune responses to S. aureus bacteremia, such as splenomegaly and cytokine/chemokine production." (PMID 36808423, 2023). "In Staphylococus aureus bacteremia mouse model, aging and TLR2 deficiency impair the immune responses in distinct patterns." (PMID 36808423, 2023). "It is most likely that aging determines lethality in bacteremia but TLR2 affects both mortality rates and weight loss." (PMID 36808423, 2023). "Toll-like receptor 2 (TLR2) recognizes Staphylococcus aureus (S. aureus) which causes bacteremia with high mortality in the elderly." (PMID 37258615, 2023). "Our data show that both aging and TLR2 deficiency impair the immune responses to S. aureus bacteremia in distinct patterns." (PMID 36808423, 2023). "In summary, we demonstrate that aging and TLR2 deficiency impair the immune response to S. aureus bacteremia in distinct ways." (PMID 36808423, 2023). "Future studies should define the roles of TLR2 in susceptibility of immunocompromised populations, particularly those at the extremes of age, to SE bacteremia." (PMID 20404927, 2010). "After i.v. challenge with SE, early (1 h) cytokine/chemokine production and subsequent clearance of bacteremia (24–48 h) were markedly impaired in TLR2-deficient mice." (PMID 20404927, 2010). "TLR2-deficient mice demonstrated impaired clearance of SE bacteremia, with dramatically and significantly higher peripheral blood concentrations of SE at 24 and 48 h." (PMID 20404927, 2010). "This shows that the aged WT and partially TLR2−/− mice cannot further increase IgG in response to bacteremia infection, which may be important for less immune clearance in both aged and TLR2 deficient mice." (PMID 37258615, 2023). "In contrast, weight loss during S. aureus bacteremia seemed to be mostly TLR2 dependent." (PMID 36808423, 2023). "So far, the regulation of humoral immune response underlying the age-related, TLR2 and S. aureus bacteremia remains largely unknown." (PMID 37258615, 2023). "TLR2 deficiency causes the overgrowth of S. aureus in the kidneys during bacteremia." (PMID 36808423, 2023). "Interestingly, the increased mortality risk associated with S. aureus bacteremia is more controlled by aging, whereas other clinical parameters, such as weight loss and kidney abscesses, are more TLR2 dependent." (PMID 36808423, 2023). "TLR2 downregulation and IL-6 and IL-10 concentrations suggestive of immune dysregulation during early bacteremia may be associated with mortality from SAB." (PMID 33256638, 2020). "This suggests that engagement of the TLR2 pathway can have detrimental effects on the developing brain, and may play a role in neonatal brain injury associated with bacterial sepsis." (PMID 21573120, 2011). "TLR2-deficient mice injected intravenously with SE demonstrated reduced early (1 h) cytokine/chemokine induction and selectively and markedly impaired subsequent clearance of bacteremia at 24–48 h." (PMID 20404927, 2010). "Impaired production of cytokines in response to intravenous SE was associated with impaired clearance of bacteremia, suggesting that TLR2-mediated cytokine production may contribute to clearance of SE in vivo." (PMID 20404927, 2010). "In a nonhuman primate model, hyaluronidase activity decreases neutrophil bactericidal activity by interfering with TLR2/TLR4 signaling, and a hylB mutant deficient in hyaluronidase activity was deficient in establishing fetal invasion and bacteremia." (PMID 38842305, 2024). "This implies that only IgG1 and IgG2a levels increased due to the bacteremia infection but in a higher proportion in the young versus the aged in both WT and TLR2−/− mice." (PMID 37258615, 2023). "To answer these questions, we used our well-established S. aureus bacteremia model with old and young as well as TLR2-knockout mice." (PMID 36808423, 2023). "Our finding shows that in general humoral immune responses to S. aureus bacteremia are regulated by both aging and TLR2." (PMID 37258615, 2023).
bacteremia (continued). "In summary, our data demonstrate a subtle relationship between humoral immune response, aging, and TLR2 in S. aureus-induced bacteremia." (PMID 37258615, 2023). "Our results, although not statistically significant, are consistent with these findings, suggesting that TLR2-activity triggered upon bacteremia onset is important for early bacterial clearance and more favorable clinical outcomes of SAB." (PMID 33256638, 2020). "The use of TLR-2 knock-out (KO) in bacteremia models with neonatal and adult mice resulted in delayed clearance, especially at early time-points after infection." (PMID 28824556, 2017). "TLR2 has previously been shown to mediate recognition of live S. epidermidis and clearance of bacteremia." (PMID 26857577, 2016). "Taken together, we show that in an acute model of periodontal infection recurrent bacteremias lead to strong, TLR2-dependent mobilization of endothelial progenitors from the bone marrow to the circulation." (PMID 23355901, 2013). "Even though, TLR2 signaling plays a major role in the activation of B-1 cells, it is not the only TLR required for response against B. hermsii, as MyD88 knockout mice suffer from more severe episodes of bacteremia with B. hermsii than TLR2 knockout mice." (PMID 20625435, 2010). "We have demonstrated for the first time the importance of TLR2 in recognition of live SE as measured by whole blood cytokine production and highlight a selective role of TLR2 in clearance of SE bacteremia." (PMID 20404927, 2010). "We have demonstrated a selective role of TLR2 in clearance of SE bacteremia, the most common, harmful and costly clinical manifestation of SE infection." (PMID 20404927, 2010). "Our data strongly suggest that both age and TLR2 are crucial host factors in S. aureus bacteremia." (PMID 36808423, 2023). "Both aging and TLR2−/− increased the levels of anti-staphylococcal IgM in bacteremia." (PMID 37258615, 2023). "Furthermore, in preclinical models of S. epidermidis bacteremia or subcutaneous/soft tissue foreign-body infection, an up-regulation of TLR-2 and the adaptor molecule MyD88 has been observed upon infection." (PMID 28824556, 2017). "TLR2 signaling was confirmed to accelerate the clearance of S. epidermidis bacteremia, but TLR2−/− mice could still resolve a bloodstream infection." (PMID 26857577, 2016). "Additionally, animal survival was improved and bacteremia was attenuated in the MyD88-/- (100%) and TLR2-/- (100%) mice in comparison with the irinotecan-injected WT mice (P<0.05)." (PMID 26440613, 2015). "WT and TLR2−/− mice infected with either strain had similar levels of bacteremia." (PMID 23724118, 2013). "The role of TLR2 in responses of primary blood leukocytes to live SE and in clearance of SE bacteremia, the most common clinical manifestation of SE infection, is unknown." (PMID 20404927, 2010). "We demonstrate for the first time that live SE, which elaborates a TLR2-activating soluble factor (SE-S), can activate primary cells via human and murine TLR2 in vitro and that TLR2 substantially and selectively contributes to clearance of SE bacteremia in vivo." (PMID 20404927, 2010). "Conversely, enhancing TLR2-mediated host defense may hasten clearance of SE bacteremia; consistent with protection against bacteremia afforded by hypermorphic alleles of TIRAP, a signaling molecule downstream of TLR2." (PMID 20404927, 2010). "TLR2 mediates recognition of live SE and clearance of SE bacteremia in vivo." (PMID 20404927, 2010). "Novel TLR2 antagonists in biopharmaceutical development may reduce SE-induced inflammation, but may also impair clearance of SE bacteremia." (PMID 20404927, 2010). "Although peak bacteremia was the same in B6 and TLR2 KO mice (day 3 post-inoculation), LVS clpB clearance was delayed in the spleen, liver, and lung of TLR2 KO mice." (PMID 25250027, 2014). "The strong activation of TLR2 and CD14 was also observed in murine brain parenchyma after the presence of S. suis bacteremia." (PMID 20937098, 2010).
bacteremia (continued). "Like the previous studies, after bacteremia infection, we found that in S. aureus infected mice the total IgG levels were similar in all mice and neither affected by age nor the lack of TLR2." (PMID 37258615, 2023). "Our results show that age but not TLR2 tightly controls the IgM production in both healthy conditions as well as in responses to S. aureus bacteremia." (PMID 37258615, 2023). "In bacteremia infection, aged mice failed to mount proper IgM response in both wild-type (WT) and TLR2−/− mice, whereas IgG response was impaired in both aged and TLR2−/− mice." (PMID 37258615, 2023). "Older mice had significantly lower fold changes of spleen weight than young mice irrespective of TLR2 expression, suggesting that the capacity of splenocyte proliferation in response to S. aureus bacteremia is mainly dependent on age." (PMID 36808423, 2023). "Consistent with the literature, in this study, patients who died from SAB had significantly higher IL-6 and IL-10 levels during early-stage bacteremia, and patients who died within 7 days of SAB onset further displayed a significantly elevated IL-10/TNF-α ratio and TLR2 downregulation." (PMID 33256638, 2020). "All these data suggest that TLR2 accelerates the clearance of bacteremia; however, our data and the work of Bi and coworkers suggest that TLR2 is not necessary for the clearance of bloodstream bacteria." (PMID 26857577, 2016). "However, IgG subclasses were not altered after bacteremia infection in either young or aged TLR2−/− mice." (PMID 37258615, 2023). "Indeed, when we compared the response in the healthy towards the bacteremia infection the level of IgG was three times higher in WT-young mice, with only a minor induction in TLR2−/− mice and no alteration in old WT mice." (PMID 37258615, 2023). "Thus, in case of a bacterial sepsis, the inflammatory response in the lung will never be induced by exclusive activation of TLR2 or TLR4 but always by costimulation of TLR9." (PMID 21547259, 2011). "Although SE-derived factors can activate human cultured cells via TLR2 and NOD2, their relative contribution to responses of primary leukocytes to live SE in vitro or clearance of SE bacteremia in vivo- experimental settings that may most closely mimic clinical infection- are undefined." (PMID 20404927, 2010).